AFP (alpha fetoprotein)
Diseases named in the same sentence as AFP in open-access papers (continued):
Sharing a sentence is not in itself a finding about the gene and the disease.
cancer (continued). "In particular, a variety of cancers display changes in glycan structures of serum proteins such as IgG, α-fetoprotein (AFP), prostate-specific antigen (PSA) and haptoglobin (Hp)." (PMID 28052004, 2017). "We further tested the uptake efficiency of ISONA by different histological types of human cancer cells with undetectable levels of AFP expression." (PMID 28109303, 2017). "The TSmiR test showed an overall sensitivity of 98%, and a specificity of 48% (control versus cancer), based on combination of the different miRs, outperforming the serum markers AFP and hCGB." (PMID 28938535, 2017). "The diagnostic efficacy of APAR for predicting HCC has superiority than AFP in diagnosing HCC from non-cancer control, as well as from CHB patients." (PMID 28827721, 2017). "Voltammetic stripping analysis was also used for the determination of three cancer biomarkers, AFP, CEA and CA19-9 in a single run by employing CdS, PbS and Au nanoparticles to prepare the electrochemically distinguishable signal tags." (PMID 28448466, 2017). "The outcome of this research indicate the potentials of OV-6, M2-PK and TGF-β as liver tumour biomarkers besides AFP, while it attests the beneficial effect of ChV extract as an anti-cancer treatment." (PMID 29268718, 2017). "The use of AFP to selectively kill AFP-positive cells was later reproduced in human xenograft cancers in an athymic mouse model." (PMID 28165834, 2017). "Second, AFP rapidly decline to normal range after radical eradication of cancer cells and rise again after recurrence." (PMID 29156744, 2017). "The detection of cancer biomarkers, such as alpha-fetoprotein, can be used to pre-screen patients to enhance the detection accuracy." (PMID 28009002, 2016). "In fact, fucosylated alpha-fetoprotein (AFP), AFP-L3, has been developed as a biomarker and approved for the early detection of liver cancer, being the most successful glyco-related cancer biomarker to date." (PMID 27136596, 2016). "We demonstrate the successful use of Eu3+-activated core–shell–shell nanoprobes for in vitro upconverting/downshifting luminescent detection of a cancer biomarker of alpha-fetoprotein." (PMID 30155152, 2016). "Preoperative FLEP chemotherapy [a combination of chemotherapy with 5-fluorouracil (5-FU), leucovorin (LV), etoposide (VP-16) and Cis-diamminedichloroplatinum (CDDP)] was reported to improve the prognosis of AFP-producing GC owing to down-staging of cancer." (PMID 27995033, 2016). "For example, carcinoembryonic antigen (CEA), and α-fetoprotein (AFP) are recognized as typical biomarkers for cancers." (PMID 27916961, 2016). "Further studies are required to determine the effect of the etiology of the disease on the GP73 signal strength, the diagnostic accuracy of GP73 in detecting early HCC or cancer recurrence and the value of a combination of GP73 and AFP." (PMID 25780444, 2015). "Studies have shown that AFP plays double roles in both inhibiting the immune system and promoting the growth of cancer cells." (PMID 25983748, 2015). "Previous reports have also established that other promoters, such as the AFP, Rad51C, human telomerase reverse transcriptase (hTERT), and midkine promoters, are expressed in a majority of human cancers." (PMID 26498690, 2015). "This methodology is particularly relevant for cancer tissues, as most known cancer biomarkers are glycoproteins or carbohydrate antigens, including AFP for HCC." (PMID 26501333, 2015). "This role of AFP in cell proliferation appears to be driven through one of the most activated signaling pathways in cancer, the PI3K/AKT pathway." (PMID 25822740, 2015). "Some studies have shown that CXCR4 plays a pivotal role in on metastasis of cancer cell, while we found that AFP stimulated CXCR4 expression by activating PI3K/AKT signaling." (PMID 25815363, 2015).
cancer (continued). "To elucidate the signaling pathway involved in the AFP modulation, we assessed the role of the two most activated signaling pathways in cancer cells: the PI3k/Akt/mTOR and the MAPK/ERK pathways." (PMID 25822740, 2015). "Interactome analysis revealed direct or indirect interaction of these proteins with current standard HCC biomarker AFP as well as with other important proteins which are either previously characterized as HCC biomarkers or are involved in cancer pathogenesis." (PMID 26414287, 2015). "We have recently confirmed that AFP promotes cancer cell proliferation, enhances Ras expression, and activates PI3K/AKT signals to enhance Src expression." (PMID 25682869, 2015). "Elevated levels of the proteins CEA, AFP, hCG-β, FER, CA15-3, CA19-9, and CA125 can be associated with lung, pancreatic, breast, colorectal, and other types of cancer." (PMID 25381564, 2014). "The most aggressive of these is the cancer germinal ovary of endodermal sinus with an astonishing increase of alpha-fetoprotein and beta fraction, as well as malignant neoplasm with an adverse forecast." (PMID 25371706, 2014). "AFP is expressed in plasma so it cannot be simply compared, but we believe EpCAM serves well as a marker for locating the cancer stem cells." (PMID 24696843, 2014). "The univariate Cox regression analysis demonstrated that the prothrombin time, AFP, portal vein invasion, advanced cancer stages, poor differentiation, and higher PTP4A3/PRL-3 expression correlated with both cumulative OS and RFS." (PMID 23064776, 2013). "There are numerous classical cancer markers used clinically, such as alpha fetoprotein (AFP) and carcinoembryonic antigen (CEA), meanwhile, increasing numbers of new cancer markers are being discovered, such as vascular endothelial growth factors (VEGF)." (PMID 24340065, 2013). "Recently, the national comprehensive cancer network guidelines also proposed AFP as a alternative tool for diagnosing HCC." (PMID 23282286, 2013). "Three different cancer biomarkers (AFP, CEA, VEGF) were analyzed to compare the analytical performance of both assay formats." (PMID 24340065, 2013). "Although the detection of serum AFP level is well established in the screening and diagnostic purpose for HCC, a major shortcoming is that serum AFP is insensitive for the early cancer detection." (PMID 27335826, 2013). "Normal serum alpha-fetoprotein, carcinoembryonic antigen, and cancer antigen 19–9 are typical lab values of patients with HEHE." (PMID 23533870, 2013). "Homeotic genes that function in cell specialization by regulating differentiation marker expression such as AFP are misregulated in cancer." (PMID 23840771, 2013). "Fucosylated alpha-fetoprotein (AFP) is widely used in the diagnosis of hepatocellular haptoglobin have also been found in sera of patients with various carcinomas." (PMID 24255851, 2013). "Change in fucosylation of glycoproteins such as fucosylated alpha-fetoprotein (AFP) is one of the most representative types of glycan-related cancer biomarkers." (PMID 24970126, 2012). "In the current study, median AFP level in HCV-associated HCC was 37 ng/ml, compared with 1000 ng/ml in HBV-associated HCC, and only 27% among HCV-associated cancers produced serum AFP greater than 100 ng/ml, compared with 65% in of HBV-associated HCC." (PMID 22681852, 2012). "Many cancers often re-express fetal or embryonic genes, and AFP gene expression is reactivated in HCC cells." (PMID 23173703, 2012). "The average concentration of AFP in serum often increases under cancer conditions from 5–20 ng mL−1." (PMID 22164043, 2011). "Although some clues to the functional roles of both GIP-34 and GIP-8 have been sporadically reported, the mechanism of anti-cancer growth of the two AFP-derived peptides has yet to be clarified." (PMID 24212829, 2011). "In this paper we show that the protein most significantly up-regulated in EC 14 Ds testes was the well-known cancer-specific marker AFP." (PMID 21573244, 2011).
cancer (continued). "Like other well-known cancer biomarkers such as alpha-fetoprotein (AFP), carcinoembryonic antigen (CEA) and CA-125, SEPT9 is implicated in both embryogenesis and oncogenesis." (PMID 22168215, 2011). "An analytical application in microarray format of a cancer marker (alpha-fetoprotein, AFP) and a selective herbicide (atrazine) on four types of audio-video disk was conducted." (PMID 22319260, 2010). "In the context of cancer, dual specificity T cell epitopes have been identified for alpha-fetoprotein, NY-ESO-1, and carcinoembryonic antigens." (PMID 19901990, 2009). "Using a low cut-off point (CEA 2.5 microgram/l, AFP 5 microgram/l, and hCG 3 i.u./l) there is an unacceptably high proportion of control patients having one or more positive tests (42-54%) compared to cancer-bearing patients (67%)." (PMID 6169360, 1981). "Currently, AFP is the sole biochemical marker used to diagnose this cancer." (PMID 41510183, 2026). "Serum AFP plays a significant role in discriminating between benign and malignant tumors." (PMID 41255769, 2025). "We further noted an upregulation in the serum levels of carcinoembryonic antigen (CEA) and alpha-fetoprotein (AFP), which are commonly used clinical cancer markers, following S. flexneri C.11 treatment for 6 weeks, with a more significant difference at 14 weeks." (PMID 40911847, 2025). "Various biomarkers have demonstrated clinical utility in early cancer detection and screening, such as alpha-fetoprotein (AFP), carcinoembryonic antigen (CEA), prostate-specific antigen (PSA), beta-human chorionic gonadotropin (β-Hcg), and carbohydrate antigen 19 − 9 (CA-19-9)." (PMID 40721833, 2025). "HBx drives expression of alpha‐fetoprotein (AFP), which is associated with 70%–90% of patients with hepatocyte tumours; it can activate the PI3K/AKT signalling pathway to promote the transformation of liver cells into cancer." (PMID 39720865, 2025). "Additionally, immunohistochemical analysis revealed human epidermal growth factor receptor two (HER2) negativity and AFP positivity in numerous cancer cells." (PMID 40922714, 2025). "Various types of AFP-based cancer vaccines have been developed to date." (PMID 40430002, 2025). "It has been proposed that HACs may originate from hepatic differentiation of other tissue components and that these cancer cells are also capable of producing AFP and secreting it into the serum." (PMID 40740864, 2025). "Shared antigens may also include oncofoetal antigens like alpha-fetoprotein (AFP), which are expressed during foetal development but are re-expressed in certain cancers." (PMID 40433416, 2025). "Regarding proteomic biomarkers, the clinical applications of cancer-associated antigens such as CEA, AFP, CA199, and CA125 have been extensively researched (Leja and Linē, 2021), yet their effectiveness remains constrained owing to low sensitivity and accuracy, typically around 30%." (PMID 41145761, 2025). "It is more specific than AFP and is derived from cancer cells." (PMID 38817995, 2024). "One could consider cancer cells acquiring the ability to produce AFP during cancer cell differentiation, invasion, and proliferation." (PMID 38817451, 2024). "HGF/c-Met activation may induce the dedifferentiation of common adenocarcinoma cells, which revert to a stem cancer cell phenotype and produce AFP or hepatoid differentiation." (PMID 38817451, 2024). "Alpha-fetoprotein (AFP) is a key marker for early cancer detection and assessment." (PMID 39337777, 2024). "AFP is particularly useful as a biomarker for diagnosing HCC, especially in countries with a high prevalence of cirrhosis and hepatitis B and C, which are risk factors for this cancer." (PMID 39685591, 2024). "Cancer stage and AFP levels were missing in 7 (12%) and 5 (8%) patients, respectively." (PMID 38230223, 2024). "Previous studies have reported AFP could directly promote the proliferation and growth of cancer cells, as well as block cell apoptosis." (PMID 38408930, 2024).
cancer (continued). "Thus, exogenous umbilical cord-derived MSCs can inhibit growth and promote the apoptosis of cancer cells by downregulating AFP, Bcl-2, and survivin." (PMID 38660138, 2024). "More than 40% of HCCs have normal AFP levels, and AFP values can also be raised in other cancers." (PMID 39410020, 2024). "Moreover, leveraging AI to integrate CNA, FS, and AFP data and calculate the cancer score (PHCC), the final PHCC value decreased from 0.999 to 0.871, higher than the cutoff value of 0.475, indicating a positive MRD status." (PMID 39704423, 2024). "Other diagnostic tools and biomarkers showing promising results for early stage cancer detection, such as the GALAD (gender, age, L-AFP3, AFP, and des-carboxyprothrombin) risk score, have potential for significant impact through improving surveillance sensitivity." (PMID 39123472, 2024). "There are two main theories regarding AFP-producing cancers." (PMID 38817451, 2024). "Hence, it is conceivable that AFP-positive NETT is an unfavorable type of cancer such as seen in the present case." (PMID 37721573, 2023). "Furthermore, in the high-risk group, AFP, CST6, CGB5, and ELANE were significantly expressed, indicating their potential roles as cancer-promoting genes in the development of STAD." (PMID 37377916, 2023). "However, when people suffer from certain malignant tumors, AFP concentrations in serum are usually higher than 25 ng·mL−1." (PMID 37232911, 2023). "In addition to the function of carriers, there have been attempts to design special AIFs to prevent AFP from combining with cytoplasmic proteins, which would block the activation of the cellular pathways responsible for the growth of cancer cells." (PMID 36768863, 2023). "In this study, we examined the mRNA expression of essential CmPn players, including the CSC (CCM1-3), mPRs (PAQR5-9, PGRMC1/2), and nPRs (PGR1/2), along with the current liver biomarker AFP, across various liver tissue and cancer types, along with patient clinical information." (PMID 36980321, 2023). "AFP-GC is a distinct type of GC, in which AFP can be tested in patients’ serum and/or cancer cells." (PMID 37588998, 2023). "AFP is a tumor marker used to detect and diagnose certain cancers." (PMID 37444523, 2023). "In addition, healthy controls possibly had a low level of linc01930 and a high level of IFN-β to show false positive results, for example, the clinical use of alpha-fetoprotein in live cancer." (PMID 36769337, 2023). "This system can detect three cancer markers (AFP, CEA, and PSA)." (PMID 37998152, 2023). "When the different biochemical mechanisms and oncogenes of AFP-GC are revealed, it may be possible to use this information in the therapeutic management of this cancer." (PMID 37354221, 2023). "Studies were performed to investigate the use of recombinant human AFP (ACT-101) conjugated with maytansinoid toxins for targeted toxin delivery to cancer." (PMID 37016369, 2023). "ACT-101-maytansinoid conjugates represent a more effective strategy in that they take advantage of the natural function of AFP as a carrier protein to deliver a toxic payload to the cancer cell." (PMID 37016369, 2023). "Throughout the first year of life, AFP levels can remain high, which can potentially mask various conditions from the neurological, metabolic, hematological, endocrine, and early childhood cancer groups." (PMID 37686577, 2023). "In this study, we identified the mechanism by which tAFP reduces the immune stimulatory activity of DC, and also show increased glycolysis, decreased mitochondrial dependence and increased lactate secretion in poorly stimulatory DC impacted by cancer cell-derived factors (AFP)." (PMID 37938561, 2023). "Serum TK1 was more sensitive than CEA and AFP in discovering people with malignant tumors." (PMID 37373974, 2023).
cancer (continued). "HCC with minimal vascular invasion, metastasis, and good prognosis is named the “Jekyll phenotype”, while the poorly differentiated HCC subset with frequent vascular invasion and metastasis, cancer stem cell features, and high serum Alpha fetoprotein levels, is named the “Hyde phenotype”." (PMID 35053606, 2022). "Furthermore, Wilson and Nil established another biosensor for detecting seven cancer biomarkers namely CEA, hCG, AFP, CA125, CA15-3, ferritin, and CA19-9, that are linked to various forms of cancer." (PMID 36560548, 2022). "Thought to be one of the immunological parameters produced by macrophages, AIM—which is different from AFP or DCP produced by cancer tissue—may be a unique biomarker for HCC." (PMID 34981443, 2022). "MiR-494 promotes metastasizing and cancer invasiveness and it can also act as a biomarker for predicting the risk of reoccurrence in AFP-negative HCC patients." (PMID 35326644, 2022). "Additionally, the use of AFP fragments that synergize with drugs can selectively destroy cancer cells." (PMID 36181321, 2022). "Also, AFP can be involved in cellular adaptation to oxidative, genotoxic, and metabolic stress during embryonic development and cancer growth." (PMID 36670957, 2022). "The Hyde phenotype is defined by cancer stem cell features, high serum alpha-fetoprotein (AFP) levels, vascular invasion, and multi-organ metastasis, where EMT and angiogenesis may occur." (PMID 35053606, 2022). "Elevated AFP levels could be found in different cancers, and hepatocellular carcinoma is the most common." (PMID 36553184, 2022). "Using a two-step transcriptional amplification strategy with the AFP promoter may enhance expression while maintaining cancer specificity." (PMID 35857843, 2022). "Using the designed reader system, cancer markers such as alpha-fetoprotein (AFP), carcinoembryonic antigen (CEA), and prostate-specific antigen (PSA) could be detected with a detection limit of 0.01 ng/mL." (PMID 36236497, 2022). "A biopsy, imaging tests such as ultrasound, CT, or CAT scan, or testing for the chemical Alpha-Fetoprotein (AFP) in the blood, which may be produced by cancer cells, are all options for cancer screening (MRI)." (PMID 35265300, 2022). "Interestingly, when we divided HCC patients into YTHDF3 low-expression group and YTHDF3 high-expression group according to IHC staining scores of carcinoma tissue, we found that serum AFP level was significantly elevated in YTHDF3 high-expression group." (PMID 36471428, 2022). "Because AFP is a growth-promoting factor, it mostly promotes the growth of cancer cells." (PMID 33898423, 2021). "Similar to the cytokine profiling results, most of the cancer‐associated proteins, such as ANGPTL4, KLK5, GAL3, VIM, HERs, CAPG, HO, CTSD, and AFP were produced at higher levels on the aged matrix, but were reduced to young matrix levels after LOX siRNA treatment." (PMID 34617419, 2021). "Therefore, attention should also be paid to distinguish a cancer thrombus from a benign thrombus by the combined judgment of imaging features and alpha-fetoprotein levels before anticoagulant treatment." (PMID 34007837, 2021). "Reports of AFP-inhibiting fragments (AIFs) for the treatment of cancer." (PMID 33898423, 2021). "AFP delivers nutrients, suppresses immunity and stimulates the growth of cancer cells." (PMID 33898423, 2021). "The HBV-related HCC patients were significantly younger (p < 0.001) and had better Child-Pugh score (p = 0.027), FIB-4 index (p < 0.001), M2BPGi levels (p = 0.003), a more progressive cancer stage (p < 0.001), and higher AFP levels (p < 0.001) than the HCV-related HCC patients." (PMID 34885089, 2021).